INS (insulin)
Diseases named in the same sentence as INS in open-access papers (continued):
Sharing a sentence is not in itself a finding about the gene and the disease.
Hyperglycemia (continued). "Increased bone expression of osteotesticular protein tyrosine phosphatase (ESP or OST-PTP) also occurred with HYP mice consistent with the observed hyperglycemia and abnormal insulin/leptin levels." (PMID 24839967, 2014). "Mild hyperglycemia and persistently elevated serum insulin levels were observed in HF male mice in the current study, similar to female BL6J mice from Taconic (Denmark) placed on 58% kcal fat diet, which do not harbor the NNT mutation." (PMID 24505268, 2014). "Impaired insulin secretion and insulin action led to an accumulation of glucose in the blood (hyperglycaemia), with adverse effects on health." (PMID 24744783, 2014). "In diabetic mice, HemoHIM effectively improved hyperglycemia and glucose tolerance compared to the diabetic control group as well as elevated plasma insulin levels with preservation of insulin staining in pancreatic β-cells." (PMID 25045390, 2014). "After 5 days net hepatic (NHGU) and muscle (MGU) glucose uptake and oxidation were assessed at euglycemia (120 mg/dl) and hyperglycemia (200 mg/dl) in the presence of basal insulin." (PMID 24465939, 2014). "A second systematic review found two trials that compared use of insulin infusion for treatment of hyperglycaemia." (PMID 24548745, 2014). "A basal plus approach, incorporating the rapid acting analogue, insulin glulisine, acknowledges the importance of addressing post-prandial hyperglycemia in reducing HbA1c in this patient group." (PMID 24886287, 2014). "The protocol of decreasing stress-induced hyperglycemia involves insulin; however, the effect of insulin therapy on lung tissue is not clearly understood." (PMID 25278226, 2014). "It is well known that ZDF rats exhibit severe hyperglycemia and decreased insulin level along with the exhaustion of pancreatic beta cells." (PMID 24895641, 2014). "Reduced glucose uptake not only results in hyperglycemia, which feeds back to stimulate further insulin release by the pancreas thereby creating or exacerbating hyperinsulinemia, but also leads to cellular and target organ dysfunction." (PMID 25101057, 2014). "The hypouricemia is also consistent with the hyperglycemia and observed changes in insulin, leptin and adiponectin." (PMID 24839967, 2014). "In the second situation, catecholamines suppress insulin secretion, with consequent hyperglycemia and free fatty acid accumulation plus decreased glucose utilization." (PMID 24715906, 2014). "Hyperglycemia induces the production of IL-1β, which interferes with insulin signaling and has cytotoxic effects on beta cells, leading to impaired insulin secretion." (PMID 25053966, 2014). "As such, we demonstrate that administering a small dose of rapid-acting insulin with a carbohydrate bolus before exercise is effective in limiting pre-exercise hyperglycaemia and preventing hypoglycaemia during and immediately after exercise." (PMID 24858952, 2014). "Branched-chain amino acids are involved in gluconeogenesis, and insulin signaling during hyperglycemia leads to a decrease in gluconeogenesis." (PMID 24465478, 2014). "In insulin resistant, insulinopenic multi-low dose, streptozotocin/high-fat diet mice, XMetS also markedly improved fasting hyperglycemia and normalized glucose tolerance." (PMID 24533136, 2014). "Glycemic clamps were performed to assess insulin secretion during controlled hyperglycemia and hypoglycemia." (PMID 24594704, 2014). "Critically ill children with severe hyperglycemia initially present decreased β-cell function and insulin sensitivity." (PMID 24628829, 2014). "In the fasting state, hyperglycemia is directly related to hepatic glucose production, which in turn, along with the decreased insulin production or increased insulin resistance, is responsible for the hyperglycemia in the postprandial state." (PMID 25346724, 2014).
Hyperglycemia (continued). "It is noteworthy that the hyperglycemia was more severe when flies were fed an HSD, with the extent of hyperglycemia similar to what is observed in insulin-resistant flies or flies with their IPCs ablated." (PMID 24609035, 2014). "Administration of resveratrol into the brain improved insulin sensitivity and normalized hyperglycemia; however, the underlying synaptic mechanisms are not fully understood." (PMID 24454277, 2014). "Adipocytes exposed to hyperglycemia display reduced insulin sensitivity, partly explained by reduced insulin-stimulated glucose uptake and increased inflammatory response including PAI-1 and IL-1β." (PMID 25143800, 2014). "Insulin plays a key role in controlling hyperglycemia in T1DM patients, and the available methods of delivery include syringes, pumps and jet injectors and pens." (PMID 25364717, 2014). "Islets were strikingly smaller and irregular and insulin expression and secretion were reduced, accompanied by mild hyperglycemia." (PMID 25181416, 2014). "This idea was tested with daily injection of neutral protamine Hagedorn (NPH) insulin in chronic hyperglycemia in STZ diabetic." (PMID 24842144, 2014). "The explanation relates to the fact that chronic hyperglycemia per se impairs insulin secretion (glucose toxicity in T2D)." (PMID 25548795, 2014). "In contrast, when compared with sliding-scale insulin, basal-bolus insulin was more frequently used in managing severe or acute hyperglycemia secondary to cardiovascular diseases and acute exacerbation of bronchial asthma (15 and 6 cases, respectively)." (PMID 25181406, 2014). "In our patients, there was a reduction both in β-cell function and in insulin sensitivity at the time of diagnosis of the hyperglycemia." (PMID 24628829, 2014). "Fasting hyperglycemia and more than 50% elevated plasma fasting insulin levels further substantiated the conclusion that these mice were insulin resistant." (PMID 25233471, 2014). "Recent reports on human ESC-derived insulin-producing cells and demonstration of their capability to treat artificially induced hyperglycemia in mice substantiate their therapeutic prospects." (PMID 24679123, 2014). "We performed a prospective study where we carefully lowered hyperglycemia by insulin administration during the surgery, and for the first time we monitored immediate insulin effects on lung physiology and gene transcription." (PMID 25278226, 2014). "In this model, the oral chemical chaperone treatment of obese diabetic mice resulted in the normalization of hyperglycemia and restoration of peripheral insulin sensitivity, thus acting as a potential antidiabetic agent." (PMID 25010593, 2014). "In that study, NPH insulin given twice daily resulted in postprandial type hyperglycemia (termed as “overall hyperglycemia” in that study) patients in a greater decrease in HbA1c compared with a combination of bedtime NPH + sulfonylurea or metformin." (PMID 23880900, 2014). "The development of severe or acute hyperglycemia resulting from the administration of corticosteroids occurs primarily because of a decrease in insulin secretion and insulin sensitivity." (PMID 25181406, 2014). "Dietary supplementation with an anthocyanin-rich extract from bilberry and blueberry improved hyperglycemia and insulin sensitivity in type 2 diabetic mice." (PMID 24637790, 2014). "Admissions were evaluated based on the insulin regimen used to manage the severe or acute hyperglycemia." (PMID 25181406, 2014). "Therapies for T2DM mainly include lifestyle changes and oral drugs to reduce the hyperglycemia and improve insulin sensitivity." (PMID 25364723, 2014). "The obvious treatment for hyperglycemia in critical illness is insulin therapy; however, the data that indicate that this approach prevents ICU acquired diaphragm weakness show that strict glycemic control with intensive insulin therapy is required." (PMID 24886999, 2014).
Hyperglycemia (continued). "Hyperglycemia was worsened in CD during two months (BG = 509 ± 22 mg/dL), and insulin was further decreased and reached to 0.51 ± 0.07 ng/dL (P<0.001)." (PMID 24842144, 2014). "In contrast Rap-treated ZDF rats have very low INS, severe hyperglycemia, and severe dysregulation of miR-29-MCL-1 axis." (PMID 25062042, 2014). "Non-insulin-dependent (type 2) DM is the dominating form, which is a metabolic disorder characterized by hyperglycemia, insulin resistance in peripheral tissues, and altered insulin secretary capacity of pancreatic β cells." (PMID 24949461, 2014). "The interaction or integration of hyperglycemia and insulin on the innate immune cells should be investigated desirably in the future." (PMID 24899891, 2014). "Hyperglycemia resulting from impaired secretion and/or action of insulin acts on bone tissue cells through an increased production of interleukin-6 (IL-6) in osteoblast line cells." (PMID 25050121, 2014). "This notion is founded on findings of maternal hyperglycemia-induced enhancing fetal insulin secretion, potentiating tissue growth—macrosomia—via fetal IGF-1." (PMID 25763406, 2014). "Transplanted MSCs can home to the pancreas and promote PDX-1 and insulin expression in the islets to normalize hyperglycemia, and these MSCs have immunoregulatory effects." (PMID 25364723, 2014). "T2D is characterized by relative or absolute shortage of insulin secretion and hyperglycemia, and hyperglycemia control plays a fundamental role in management of T2D." (PMID 25121493, 2014). "The model is characterised by a pre-diabetic state during which increasing insulin resistance drives hyperglycaemia." (PMID 25167060, 2014). "A single dose of alloxan (120 mg/kg) produced a decrease in insulin level, hyperglycemia, elevated total lipids, triglycerides, and cholesterol and decreased the high-density lipoproteins." (PMID 25114914, 2014). "When cells in the body become resistant to the effects of insulin, blood glucose levels rise, resulting in hyperglycemia." (PMID 25071557, 2014). "This is at variance with the human condition, where overt hyperglycemia persists following a phase of compensatory insulin hypersecretion." (PMID 24809394, 2014). "Over a mean (± S.D.)/median (range) follow up period of 6.71 (±4.75)/6.52 (0.1–17.5) years, twenty-two (49%) children developed hyperglycaemia requiring insulin treatment." (PMID 24840042, 2014). "The observed timing of insulin response to hyperglycemia clamp is similar to the pattern observed in other species." (PMID 24594704, 2014). "Impairment to secreting sufficient insulin levels in the face of hyperglycemia leads to the pathogenesis of diabetes." (PMID 25646092, 2014). "We conclude that critically ill children with severe hyperglycemia initially have reduced β-cell function and insulin sensitivity." (PMID 24628829, 2014). "Another case report has indicated that co-infusion of HSCs and differentiated insulin-producing cells from adipose tissue-derived MSCs was able to normalize hyperglycemia in a T1DM patient." (PMID 25364717, 2014). "Liver is one of the insulin-sensitive tissues and plays an important role in the processes of hyperglycemia and dyslipidemia." (PMID 24705395, 2014). "Of these, 4 patients discontinued sitagliptin due to worsening hyperglycemia and need for intensive insulin therapy while one patient was switched from sitagliptin to a sulfonylurea due to cost." (PMID 24817885, 2014). "It is characterized by hyperglycemia resulting from defects in insulin secretion, insulin action, or both." (PMID 25593725, 2014). "In T2DM patients, impaired beta cell insulin secretion and impaired suppression of glucagon secretion from alpha cells lead to hyperglucagonemia mediated hyperglycemia." (PMID 25186493, 2014). "There was also a significant increase in the incidence of medical treatment for PDA (58% v 25%), insulin for hyperglycaemia (26% v 12%) and conjugated bilirubin >34 μmol/L (36% v 20%)." (PMID 25514973, 2014).
Hyperglycemia (continued). "In the current study we observed that women with GDM history had decreased insulin sensitivity but hyperglycemia appeared after compensatory insulin secretion mechanism failed." (PMID 25174260, 2014). "Daily oral administration of RSL (100 or 300 mg/kg) for up to eight days acutely reduced hyperglycemia and improved insulin sensitivity in high fat diet-induced obese hyperglycemic mice compared to vehicle (water) control." (PMID 24637790, 2014). "It is characterized by hyperglycemia with disturbances in the metabolism of carbohydrate, fat, and lipid metabolism resulting from defects in insulin secretion, insulin action, or both." (PMID 24812635, 2014). "Hyperglycemia stimulates secretion of insulin and amylin, reducing the secretion of glucagon; it also decreases the secretion of ghrelin, which reduces gastric emptying, via parasympathetic signal." (PMID 25003936, 2014). "Ten children (22%) developed hyperglycaemia requiring insulin therapy immediately after pancreatectomy." (PMID 24840042, 2014). "The metabolic features of STZ-induced DM animals include prompt development of profound hyperglycemia, modest hypertriglyceridemia, ketosis, and markedly reduced plasma insulin levels." (PMID 24885095, 2014). "Other factors that contribute to the insulin secretory defect include chronic glucotoxicity (damage to the ß cell from chronic exposure to hyperglycemia) and lipotoxicity (ß cell damage resulting from chronic exposure to elevated free fatty acids)." (PMID 25945127, 2014). "Recent preclinical results indicate that different types of hypothalamic neurons are endowed with the ability to mediate the hyperglycemia-lowering action of the adipocyte-derived hormone leptin in an insulin-dependent and insulin-independent fashion." (PMID 24589844, 2014). "Hyperglycemia decreased C4-fragment and C3-fragment opsonization of S. aureus recovered in peritoneal fluids, compared with euglycemic or insulin-rescued rats." (PMID 25610878, 2014). "The pathologic mechanisms of this disease are mainly attributed to impaired insulin secretion by pancreatic β-cells and insulin resistance in target tissues, including skeletal muscle and the liver, which ultimately leads to hyperglycemia." (PMID 25013896, 2014). "When dolphins were fed a big meal of fish, they had an insulin-resistant response (sustained postprandial hyperglycemia and hyperinsulinemia)." (PMID 25566195, 2014). "Stress-induced hyperglycemia has been considered an adaptive mechanism to stress up to the first intensive insulin therapy trial, which showed a 34% reduction in relative risk of in-hospital mortality when normalizing blood glucose levels." (PMID 25177798, 2014). "The vanadium salt was shown to induce a mechanism to reduce hyperglycemia and improve insulin action by increasing the glucose transporters activity via insulin receptor substrates 1 and 2 (IRS1/2) and phosphatidylinositol 3-kinase (PI 3-kinase)." (PMID 25162051, 2014). "Basal and postprandial hyperglycaemia, high postprandial insulin and C-peptide levels in the early recovery phase, and decreased QUICKI index were the markers of IR." (PMID 24433403, 2014). "Type 2 diabetes (T2D) is a chronic disease with hyperglycaemia as its characteristic feature, resulting from defects in insulin secretion and/or insulin action." (PMID 24550982, 2014). "In our mouse model, chronic hyperglycaemia not only led to a remarkable reduction in insulin granule content but also to the appearance of large areas of unstructured cytoplasm within β-cells." (PMID 25145789, 2014). "Chronic hyperglycemia does not only induce insulin secretion impairment and insulin resistance but is also involved in macrovascular and microvascular complications of several organs, sometimes long time after the exposition." (PMID 25347859, 2014). "The clamp is used to measure insulin secretion under steady state condition of controlled hyperglycemia of about 10 mmol/L." (PMID 25945127, 2014).
Hyperglycemia (continued). "The co-secretion of these two hormones complicates the diagnosis and management, as they produce a complex clinical picture, where insulin causes hypoglycaemia and EAS exerts opposite effects leading to hyperglycaemia." (PMID 24683485, 2014). "This fructose-sensitive insulin response was also seen during intravenous fructose infusion in people, and again, insulin release in response to hyperglycemia was increased by fructose." (PMID 25100436, 2014). "Therapeutic hypothermia (TH) is often used to treat out-of-hospital cardiac arrest (OHCA) patients who also often simultaneously receive insulin for stress-induced hyperglycaemia." (PMID 25349023, 2014). "Together, these data demonstrate that SOX17 expression stimulates the insulin secretory pathway within 24 hours and that continued expression promoted precocious proinsulin secretion and hyperglycemia." (PMID 25144761, 2014). "It is known that free fatty acids (FFAs) block glucose transport by inhibiting insulin’s interaction with hepatocytes and monocytes, leading to hyperglycaemia and IR development." (PMID 24433403, 2014). "After correction of hyperglycemia and ketosis with insulin therapy, plasma C-peptide concentrations were measured at 0, 0.5, 1, 2, and 3 hours after 75 g glucose oral administration." (PMID 24829925, 2014). "But although hyperglycemia can be improved by insulin administration, exogenous insulin injection cannot exactly replicate the insulin secretion from normal β cells when the blood glucose level constantly changes." (PMID 25364717, 2014). "Diabetic patients however cannot control their postprandial blood glucose efficiently due to the insufficient insulin secretion or response, which results in postprandial hyperglycemia and it is an important contributing factor for diabetic complications." (PMID 25401101, 2014). "We found for the first time that baicalein improves hyperglycemia and glucose tolerance, promotes insulin secretion, and preserves islet mass by inhibiting apoptosis in middle-aged obese diabetic mice." (PMID 25147566, 2014). "Human ESCs effectively differentiated into islet-like cells when exendin-4 was added, and these insulin producing cells ameliorated hyperglycemia in NOD/SCID diabetic mice when transplanted into these mice." (PMID 25364723, 2014). "Following the post-exercise meal, serum insulin concentrations were lower under 50% (p<0.05) resulting in 75% of patients experiencing hyperglycaemia (blood glucose ≥8.0 mmol.l−1; 50% n = 6, Full n = 3)." (PMID 24858952, 2014). "Our findings of the insulin secretion defect leading to the failure of compensatory mechanisms and development of hyperglycemia at both fasting and postprandial level are in agreement with this." (PMID 25174260, 2014). "The transplanted cells corrected the blood glucose levels and hyperglycemia for a long time concomitantly with an increase in the in vivo concentration of insulin." (PMID 24679123, 2014). "Hyperglycemia develops in T1D when insulin presenting DCs encounter naive insulin reactive T cells in the periphery." (PMID 24877157, 2014). "This circumstance impairs signal transduction in insulin signaling, which will eventually result in hyperglycemia." (PMID 25421245, 2014). "In this paper, we intend to review recent advances on the regulating effects of hyperglycemia and insulin on innate immunity, with a particular emphasis on severe burns." (PMID 24899891, 2014). "L-asparaginase induces hyperglycemia via depletion of L-asparagine and as a consequence decrement of insulin synthesis; additionally it decreases insulin secretion from pancreatic β-cells, impairs insulin receptor function, and causes hyperglucagonemia." (PMID 24716037, 2014). "Hyperglycemia can lead to increased platelet reactivity and not only hyperglycemia but insulin can also directly control platelet function by a functional insulin receptor found on human platelets." (PMID 24883111, 2014).